BRD4 (bromodomain containing 4)
Diseases named in the same sentence as BRD4 in open-access papers (continued):
Sharing a sentence is not in itself a finding about the gene and the disease.
ovarian carcinoma (continued). "However, this work has been an important step towards our ongoing and future comprehensive studies providing a better insight into BRD4 isoforms genomic and proteomic regulation and oncogenic activity in ovarian cancer." (PMID 37705995, 2023). "However, in BRD4-R3K mutant cells and deficiency of PRMT1, the metastasis was inhibited in ovarian cancer cells." (PMID 37737256, 2023). "BRD4 is known to be a critical regulator of PD-L1 expression in tumor cells, dendritic cells and macrophages by directly binding the CD274 (encoding PD-L1) gene promoter, at least in ovarian carcinoma cell-lines." (PMID 35226658, 2022). "Concerning clinical stages, BRD2 and BRD3 in advanced stage (III+IV), and BRDT in all clinical stages (I+II, III+IV) were associated with the better OS in ovarian cancer patients, although high BRD4 mRNA level showed worse OS in early-stage (I+II) patients with ovarian cancer." (PMID 35371325, 2022). "This pipeline identified 12,339 BRD4-enriched active enhancer elements in ovarian cancer cells." (PMID 35869079, 2022). "However, high BRD2 mRNA expression in grade I and BRD4 mRNA in grade III showed significantly poor OS in patients with ovarian cancer." (PMID 35371325, 2022). "In dealing with ovarian cancer, BRD4 inhibitors could re-sensitize drug-resistant cancer cells to anti-cancer drugs." (PMID 35252174, 2022). "Thus, we reasoned that co-enrichment of BRD4 and H3K27ac can be used as a surrogate to find SEs driving oncogenic processes in ovarian cancer." (PMID 35869079, 2022). "To ascertain if the enhancer was active in ovarian cancer cells and may be responsible for this increased expression, we downloaded publicly available H3K27ac and BRD4 ChIP-seq datasets and looked for the enrichment of these marks at the CSF1 enhancer region." (PMID 35406623, 2022). "Moreover, ovarian cancer has the highest overall expression of BRD4 across all TCGA cancer types and patients with increased expression of BRD4 experienced significantly reduced survival times as determined through Kaplan–Meier analysis 6,31–35." (PMID 35869079, 2022). "Given that copy number variation (CNV) has been previously identified as an important hallmark of ovarian cancer, we sought to investigate whether these BRD4-enriched super-enhancers were preferentially amplified in ovarian cancer patients." (PMID 35869079, 2022). "Consistently, according to the Kaplan Meier survival curves analysis, we also found that mRNA expression BRD4 was related with poor OS in all ovarian cancer patients, pathological grade III ovarian malignancy patients, and early clinical stage (I+II) ovarian malignancy patients." (PMID 35371325, 2022). "BRD4 disorders have been implicated in the pathogenesis of many cancers, such as AML, multiple myeloma, Burkitt’s lymphoma, diffuse large B-cell lymphoma, and breast, colon, and ovarian cancers." (PMID 35402244, 2022). "Notably, the expression of BRD4 is highest in ovarian cancer as compared to every other cancer type represented in The Cancer Genome Atlas and high expression portends a worse outcome in ovarian cancer patients." (PMID 35869079, 2022). "Importantly, in human ovarian cancer tissues, miR-765 was downregulated and negatively correlated with BRD4 mRNA upregulation." (PMID 33686960, 2021). "It is possible that, just as with TNBC, the amplification of BRD4 in HGSOC may lead to a shift in the splicing ratio of the two BRD4 isoforms resulting in BRD4-S overactivation that drives ovarian cancer pathogenesis and contribute to patients’ poor prognosis." (PMID 34758842, 2021). "BRD4 KO in ovarian cancer cells abolished the functional impact of miR-765." (PMID 33686960, 2021). "However, further studies are necessary to clarify the mechanisms behind the role of BRD4 in ovarian carcinoma." (PMID 34758842, 2021). "Thus BRD4 silencing should be the primary reason of miR-765-induced anti-ovarian cancer cell activity." (PMID 33686960, 2021).
ovarian carcinoma (continued). "In ovarian cancer, researchers found that knockdown of BRD4 could significantly decrease Notch3 expression, and a chromatin immunoprecipitation test revealed that BRD4 existed in the promoter of Notch3." (PMID 34834420, 2021). "BRD4 inhibition or silencing should be capable of inducing apoptosis in ovarian cancer cells." (PMID 33686960, 2021). "Collectively, BRD4 silencing by miR-765produces significant anti-ovarian cancer cell activity." (PMID 33686960, 2021). "In addition, mimicking lv-pre-miR-765’s actions, CRISPR/Cas9-induced BRD4 KO induced significant proliferation inhibition and apoptosis in ovarian cancer cells." (PMID 33686960, 2021). "Thus, mimicking lv-pre-miR-765-induced actions, BRD4 KO exerted significant anti-ovarian cancer cell activity." (PMID 33686960, 2021). "In addition, a pan-cancer analysis indicates that ovarian cancer is the most apparent tumor with BRD4 amplification." (PMID 34540687, 2021). "A shRNA screening study revealed that BRD4 is a promising therapeutic target of ovarian cancer." (PMID 33686960, 2021). "Since BRD4 is an important therapeutic target of ovarian cancer, we next tested whether miR-765 could alter ovarian cancer cell functions." (PMID 33686960, 2021). "miR-765-induced BRD4 silencing is able to produce robust anti-ovarian cancer cell activity." (PMID 33686960, 2021). "Moreover, CRISPR/Cas9-induced BRD4 knockout (KO)inhibited proliferation and activated apoptosis in ovarian cancer cells." (PMID 33686960, 2021). "MiR-598 expression was decreased and BRD4 was increased in the ovarian cancer cells." (PMID 32640974, 2020). "Additionally, the protein level of BRD4 in ovarian cancer cells was promoted significantly, as confirmed by Western blotting." (PMID 32640974, 2020). "circCELSR1 and BRD4 were promoted, but miR-598 was suppressed in various ovarian cancer cells." (PMID 32640974, 2020). "To test this hypothesis, we screened a repository of ovarian cancer patient-derived xenografts for BRD4 copy-number." (PMID 30036377, 2018). "Therefore, the IOSE model we generated represents the only reported cell line model for evaluation of the role of BRD4 in BRD4-amplified ovarian cancers." (PMID 30036377, 2018). "BRD4 encoding a chromatin remodeler and MLL2 encoding a H3K4 methyltransferase were the top mutant genes in colorectal tumors (62 %) and ARID1A, a chromatin remodeler gene, in ovarian carcinomas (50 %)." (PMID 29296220, 2017). "However, the correlation between ovarian cancer treatment and BRD4 inhibitors remains unclear due to the heterogeneous carcinogenic characteristics of ovarian cancer, differing from those of other cancers." (PMID 38473320, 2024). "Notably, PRMT1 affected ovarian cancer metastasis via an asymmetric methylation of BRD4." (PMID 37737256, 2023). "Therefore, miR-765 targeted and silenced BRD4 to potently inhibit ovarian cancer cell progression." (PMID 33686960, 2021). "Therefore, ectopic overexpression of miR-765 silenced BRD4 in pOC-1 ovarian cancer cells." (PMID 33686960, 2021). "Hence, transcriptional modulation of the NRG1 pathway might be one of the mechanisms through which BRD4 plays a role in ovarian cancer patients’ response to chemotherapy, however, further studies are required to validate such mechanism." (PMID 34758842, 2021). "Thus, miR-765 is a novel BRD4-targeting miRNA in ovarian cancer." (PMID 33686960, 2021). "When compared to miR-765-BRD4 mRNA expression in primary human ovarian epithelial cells (pOE-1 and pOE-2), miR-765 downregulation and BRD4 mRNA upregulation were observed in primary ovarian cancer cells (pOC-1 and pOC-2) and established cell lines (CaOV3 and SKOV3)." (PMID 33686960, 2021). "Importantly, BRD4 KO in ovarian cancer cells abolished the functional impact of miR-765." (PMID 33686960, 2021).
ovarian carcinoma (continued). "Importantly, a recent study demonstrated that the activity of BRD4 was necessary for proliferation and survival of two ovarian cell line, and the results of BRD4 inhibition in vitro or in vivo suggested that BRD4 was a potential therapeutic target for ovarian cancer." (PMID 32640974, 2020). "Therefore, we speculated that circCELSR1 promoted tumorigenesis of ovarian cancer via sponging miR-598 to increasing BRD4 expression." (PMID 32640974, 2020). "Additionally, our in vitro and in vivo results demonstrated that circCELSR1/miR-598 pathway regulated BRD4 downstream proliferation/migration related genes, suggesting that circCELSR1/miR-598 pathway regulates ovarian cancer cell proliferation and migration through BRD4." (PMID 32640974, 2020). "In epithelial ovarian cancer (EOC), BRD4-mediated SEs regulate the expression of a series of stem-related genes, including a significant cancer stem cell marker ALDH1A1." (PMID 39090713, 2024). "In both ovarian cancer cell lines, SKOV3 and OVCAR3, BRD4 expression decreased, whereas CDKN1A (p21) gene expression and degradation of the cell cycle inhibitor CDKN1B/p27KIP1 (p27) increased in a dose-dependent manner." (PMID 38473320, 2024). "Our study has validated a new BRD4 inhibitor, OPT-0139, as a promising anticancer agent for ovarian cancer treatment." (PMID 38473320, 2024). "Multiple approaches were used to explore the mechanism of PRMT1-mediated BRD4 methylation and to determine the biological functions of BRD4 and PRMT1 in ovarian cancer." (PMID 37737256, 2023). "To assess the clinical significance of our findings, we performed an IHC analysis of tissue microarray in ovarian cancer using anti-PRMT1 and anti-BRD4 antibodies." (PMID 37737256, 2023). "It has been observed that the transcriptional co-activator BRD4 is the fourth most amplified gene in HGSC, the most aggressive type of ovarian cancer." (PMID 37953273, 2023). "In order to evaluate the expression levels of BRD4 isoforms in HGSOC, we performed Wes (ProteinSimple) analysis using a panel of human ovarian carcinoma (OC) cell lines." (PMID 37705995, 2023). "We tested combinations of small-molecule CDK9 and/or BRD4 inhibitors in conjunction with Carboplatin and Paclitaxel and observed a synergistic inhibition of HGSOC ovarian cancer cell growth." (PMID 38201534, 2023). "Recently, BRD4 inhibitor JQ1 and CDK4/6 inhibitor palbociclib have been shown to inhibit HR and sensitize BRCA1/2 wild-type ovarian cancers and other cancers to PARPi." (PMID 36539830, 2022). "BRD4 inhibition using small-molecule BET inhibitors (JQ1 and I-BET151) induced robust and broad anti-ovarian cancer cell activity." (PMID 33686960, 2021). "Chromatin immunoprecipitation experiments showed that BRD4 binds directly to MYC transcription start site, as well as enhancer regions in ovarian cancer cells." (PMID 34758842, 2021). "BRD4 directly targets CD274 since the ChIP-seq assay revealed a positive correlation between CD274 promoter and BRD4 in ovarian cancer." (PMID 34088360, 2021). "Ectopic overexpression of miR-765 by lv-pre-miR-765 robustly inhibited BRD4 3’-UTR luciferase reporter activity and significantly downregulated BRD4 expression in primary and established ovarian cancer cells." (PMID 33686960, 2021). "Therefore, targeting BRD4 could be an important anti-ovarian cancer therapy." (PMID 33686960, 2021). "Increased expression of BRD4 in ovarian cancer cells resulted in an increase of ALDH activity, while diminished BRD4 activity decreased ALDH activity by direct suppression of ALDH1A1 gene expression." (PMID 34758842, 2021). "Other studies revealed that induced expression of BRD4 isoforms in ovarian epithelial cells correlates with increased expression of NRG1, which has been shown to participate in ovarian cancer cells proliferation and metastasis." (PMID 34758842, 2021).
ovarian carcinoma (continued). "RT-qPCR and western blot analysis of a panel of solid tumor cell lines showed that BRD4 is highly expressed in H526 SCLC, A2780 and ES-2 ovarian cancer, MDA-MB231 TNBC cells, and A375 melanoma cells." (PMID 32286255, 2020). "In ovarian cancer cell line SKOV3 and A2780, the mRNA and protein level of BRD4 were promoted by the transfection of pcDNA3.1-BRD4." (PMID 32640974, 2020). "A recent study reported that BET proteins regulated RAD51 in ovarian cancer cells, and we showed that knockdown of each BET family member (BRD2, BRD3, and BRD4) in DMS273 cells led to downregulation of Rad51 expression." (PMID 33134168, 2020). "Here, we provide evidence that a combination of the TKI ponatinib with the BRD4 inhibitor JQ1 or the BRD4 degrader dBET1 significantly induces apoptosis in colon, breast and ovarian cancer cells." (PMID 29899872, 2018). "In order to assess the relationship between BRD4 amplification or expression level and sensitivity towards BRD4 inhibition, we utilized Sanger cell line screening data, which provided a 3-day JQ1 IC50 on 12 ovarian cancer cell lines." (PMID 30036377, 2018). "Taken together, BRD4 suppression, either by siRNA or JQ1, adds to CHK1 inhibitor lethality in ovarian cancer cells." (PMID 28881656, 2017). "Suppression of BRD4 using specific BET bromodomain inhibitors JQ1 or I-BET151 led to robust and broad antitumor effects across various subtypes of ovarian cancer." (PMID 26575423, 2016). "We hypothesized that the increased BRD4 copy-number in these samples may be due to large-scale amplifications involving cyclin E1 (CCNE1), a known driver in endometrial, breast, and ovarian cancers, which is also located on chromosome 19." (PMID 40112818, 2025). "Concomitant BRD4 inhibition with PARP inhibitor, cisplatin, tyrosine kinase inhibitors, and MEK inhibitors has been shown to efficiently and synergistically suppress ovarian carcinoma growth." (PMID 39273015, 2024). "The pharmacological inhibition of BRD4 with BET inhibitors (BETis) JQ1 and I-BET151 substantially abrogated both the in vitro growth and in vivo tumorigenesis of ovarian cancer, and BRD4 inhibitors have been largely used in several pre-clinical studies in ovarian cancer." (PMID 39273015, 2024). "Few studies have attempted to adapt BRD4 inhibitors to treat ovarian cancer cells, and most of them have focused on the relationship between PARP inhibitors and BET inhibitors or the correlation between BRD4 expression and basic function in ovarian cancer." (PMID 38473320, 2024). "While there is a lack of extensive data regarding the impact of BRD4 inhibitors on ovarian cancer in the existing literature, our research aligns with the outcomes of previous studies." (PMID 38473320, 2024). "Interestingly, we observed an increase in the level of BRD4 and an elevated level of RNAPII phosphorylation of Ser-2 in ovarian cancer KO cells lines." (PMID 38201534, 2023). "In this investigation, we found that the BRD4 proteins were not vented in normal and ovarian cancer tissues." (PMID 35371325, 2022). "Furthermore, mRNA expression of BRD4 was notably lower in the normal ovarian cell than that in ovarian cancer ES2 and A2780 cell lines, but considerably greater than that in ovarian cancer OVCAR-3 cell line (P < 0.05)." (PMID 35371325, 2022). "In other ovarian cancer cells, including pOC-2 primary cells and established cell lines (SKOV3 and CaOV3), stable transfection of lv-pre-miR-765 similarly resulted in robust miR-765 upregulation and BRD4 mRNA downregulation." (PMID 33686960, 2021). "The expression of BRD4 is significantly higher in clinical ovarian cancer tissues than in non-malignant control tissues, whereas the levels of BRD2 and BRD3 do not significantly vary between malignant and non-malignant tissues." (PMID 34540687, 2021).
ovarian carcinoma (continued). "Although there are no studies that specifically elucidate the involvement of BRD4 in the regulation of Snail1 and Slug in ovarian carcinoma, the mechanism by which these genes promote EMT is relatively conserved amongst different types of tumors." (PMID 34758842, 2021). "As expected, the lentiviral construct encoding control anti-sense sequence, lv-antaC, did not alter BRD4 expression and ovarian cancer cell functions." (PMID 33686960, 2021). "The JQ1 compound was shown to bind to the bromodomains of BRD4, with higher affinity and stability than to other members of the BET family and it has been largely used in pre-clinical studies testing BETi in ovarian cancer." (PMID 34758842, 2021). "Pre-clinical studies demonstrated that the pharmaceutical inhibition of BRD4 or BRD4 knockdown contribute to homologous recombination defects (HRD), sensitizing ovarian carcinoma cells to Poly (ADP-ribose) polymerase inhibitors (PARPi), regardless of their BRCA mutation status." (PMID 34758842, 2021). "Indeed, a small molecular BRD4 inhibitor, JQ1, has been shown to inhibit cell proliferation and induce apoptosis, as well as increase sensitivity to cisplatin in ovarian cancer cells." (PMID 34031395, 2021). "As evidenced by CHIP-PCR, we found that the TF binding site (TFBS) of five TFs had binding events to BRD4 after it was cultured with or without CM of ovarian cancer cells, among which PRDM1 and MAF had increasing binding events after CM treatment." (PMID 32184777, 2020). "In summary, these findings lead us to conclude that the BRD4 expression is elevated in HGSOC cell lines lacking the Caspase-8 expression, and the overexpression of BRD4 significantly shortens OS in ovarian cancer patients, mainly when the Caspase-8 expression is low." (PMID 38201534, 2023). "In addition, interacting with BRD4, CBX5 can inhibit DNA damage response in ovarian cancer." (PMID 36140750, 2022). "Interestingly, the two mutant miR-765 mimics with mutations at the binding sites to BRD4 3’-UTR failed to alter BRD4 expression in ovarian cancer cells." (PMID 33686960, 2021). "None of the four lines with amplified BRD4 were derived from ovarian cancer patients." (PMID 30036377, 2018). "Consistently with this model, analysis of reverse phase protein arrays (RPPA) in the cancer genome atlas (TCGA) database revealed that ovarian carcinomas with BRD4 amplification showed significantly downregulated pMEK and pERK compared with those without BRD4 amplification." (PMID 26575423, 2016). "Interestingly, BET inhibitors inhibit ALDH activity by eliminating BRD4-mediated ALDH1A1 expression through the activation of SEs and related eRNAs, offering a theoretical basis for the clinical application of JQ1 to inhibit the growth of cisplatin-treated ovarian cancer cells in vitro and in vivo." (PMID 39090713, 2024). "There have been many studies exploring the clinical role of the BRD4 gene and the effect of BET inhibitors in ovarian cancer cell lines but not in cells directly extracted from biological specimens." (PMID 38893083, 2024). "Given the absence of BRD4-amplified ovarian cancer cell lines, we used IOSE cells stably expressing the different BRD4 isoforms at levels similar to those in patients with amplified BRD4." (PMID 30036377, 2018).